CATSPER1 (cation channel sperm associated 1)
Description:
Pore-forming subunit of the CatSper complex, a sperm-specific voltage-gated calcium channel that plays a central role in calcium-dependent physiological responses essential for successful fertilization, such as sperm hyperactivation, acrosome reaction and chemotaxis towards the oocyte.
Synonyms: CATSPER; SPGF7
Tractability: Small molecule: it belongs to a druggable protein family. Antibody: its Gene Ontology location is reachable by antibodies, with high confidence; UniProt predicts a signal peptide or a membrane-spanning region.
Target class: CatSper and Two-Pore channels; Voltage-gated ion channel; Ion channel
Gene: Protein-coding gene on chromosome 11 (66,016,752 to 66,026,479, reverse strand). Ensembl gene ENSG00000175294.
Subcellular location: Cell projection, cilium, flagellum membrane
Subcellular location (Human Protein Atlas): Principal piece
Pathways (Reactome):
Reproduction: Sperm Motility And Taxes
Gene Ontology:
Molecular function: protein binding; voltage-gated calcium channel activity; calcium-activated cation channel activity; monoatomic ion channel activity
Biological process: calcium ion transport; flagellated sperm motility; regulation of cilium beat frequency involved in ciliary motility; sperm capacitation; spermatogenesis; calcium ion transmembrane transport; monoatomic cation transmembrane transport; monoatomic ion transmembrane transport; monoatomic ion transport; transmembrane transport
Cellular component: sperm flagellum; sperm principal piece; CatSper complex; plasma membrane; membrane
Genetic constraint (gnomAD): Loss-of-function variants: 55 observed, 75.93 expected, observed/expected ratio (o/e) 0.72, 90% interval 0.58 to 0.91. The upper end of that interval is the gene's LOEUF score, 0.91, which puts it in group 3 of 6, group 1 being the genes least tolerant of losing a copy. Missense variants: 907 observed, 1,082.8 expected, observed/expected ratio (o/e) 0.84, 90% interval 0.79 to 0.88. Synonymous variants: 363 observed, 421.55 expected, observed/expected ratio (o/e) 0.86, 90% interval 0.79 to 0.94.
Homologues: Orthologues: chimpanzee CATSPER1 (99% identical), macaque CATSPER1 (85% identical), dog CATSPER1 (59% identical), pig CATSPER1 (54% identical), mouse Catsper1 (46% identical). Paralogues in human: SCN3A (22% identical), SCN1A (22% identical), SCN2A (21% identical), SCN9A (21% identical), SCN8A (21% identical), SCN5A (20% identical), SCN10A (19% identical), SCN11A (19% identical), SCN4A (19% identical), CACNA1A (19% identical), CACNA1E (19% identical), CACNA1D (19% identical), and 14 more.
Diseases named in the same sentence as CATSPER1 in open-access papers:
CATSPER1 is named in the same sentence as 22 diseases in open-access papers, as found by Europe PMC text mining. Sharing a sentence is not in itself a finding about the gene and the disease. The quoted sentences say what the papers report.
Infertility (33 papers, 2015 to 2025). "In mice, congenital ablation of CatSper1, CatSper2, CatSper3 or CatSper4 genes inhibits CatSper currents and sperm hyperactivation and causes infertility, although spermatogenesis and initial motility are unaffected." (PMID 37108159, 2023). "The Catsper1 knock-out abrogates channel formation and severely affects mouse sperm fertilization capability; similarly, patients harboring mutations in the CATSPER1 gene show infertility." (PMID 35897646, 2022). "Genetic analysis of infertile men primarily from consanguineous families with clustering of male-factor infertility, indeed, identified individuals with nonsense variants in the CATSPER1 or CATSPER3 genes as well as with a homozygous deletion of CATSPER2 and the contiguous gene STRC." (PMID 38165034, 2024). "Interestingly, men harboring mutations or deletions on CatSper1- or CatSper2-encoding genes are infertile, and sperm samples from men undergoing ARTs present diminished responses to Pg compared to control samples from normozoospermic men." (PMID 33374265, 2020). "It has been described that CATSPER1 and CATSPER2 mutations in human sperm are associated with infertility." (PMID 37108159, 2023). "Studies in human patients have been able to detect several deletions and/or mutations in different CATSPER subunits, i.e., CATSPER1, CATSPER2, CATSPER3 or CATSPERE and their association with infertility." (PMID 37108159, 2023). "Given the relevance of this channel for fertilization, CatSper1–4 and/or the auxiliary subunits become potential candidates for either the development of new methods of diagnosis and/or treatment of infertility or to be targeted for contraception." (PMID 34295893, 2021). "The higher Catsper1 expression observed in the present study aligns with findings by Al-Msaid and Al-Sallami (2018), who reported reduced Catsper1 protein expression in normospermic, asthenozoospermic, and oligozoospermic infertile men compared to fertile normospermic men." (PMID 41393904, 2025). "This is consistent with Al-Msaid and Al-Sallami's (2018) observation of a positive correlation between Catsper1 expression and sperm concentration, progressive motility, and normal sperm morphology in infertile men without a diagnosed cause." (PMID 41393904, 2025). "An intriguing aspect of our observations is that, unlike CatSper1-4 and d-null mice, which produce complete infertility, CatSperz-null males exhibit an incomplete loss of fertility." (PMID 28226241, 2017). "Likewise, CatSper1 or CatSper2 null mouse spermatozoa exhibits a decreased sperm motility, abnormal flagellar beating, as well as lacked hyperactivity and acrosome reaction, thus leading to the complete infertility of knockout male mice 4, 40-42." (PMID 33456575, 2021). "Notably, all sperm samples from the infertile patients cohort recruited in this study express lowered level, but not complete absence of CCR6 and CatSper1." (PMID 29207656, 2017).
male infertility (20 papers, 2017 to 2025). The inability of the male to effect fertilization of an ovum after a specified period of unprotected intercourse. "So far, only two studies have been investigated association of CATSPER1 gene polymorphisms with idiopathic male infertility." (PMID 35248021, 2022). "Similarly, dysregulation or mutations in the sperm-associated cation channel 1 (CatSper1) can disrupt calcium signaling, impair sperm motility, and reduce fertilization potential, contributing to male infertility." (PMID 39355314, 2024). "In general, our study provided a more understanding of male infertility as a heterogeneous disorder, and suggested that CATSPER1 (rs2845570) and SPATA16 (rs1515442) genes polymorphism are significantly associated with the risk of idiopathic azoospermia and oligospermia in Iranian Azeri population." (PMID 35248021, 2022). "Recently, association of CATSPER1 gene variants with male infertility was reported." (PMID 35248021, 2022). "In mice, genetic disruption of any one of the four sperm-specific CatSper channels (CatSper1/2/3/4) leads to male infertility by impairing sperm motility." (PMID 39469589, 2024). "Disruptions in CatSper1 regulation can lead to male infertility, affecting critical aspects of sperm physiology." (PMID 39355314, 2024). "In a rat model of CP-induced male infertility, TS effectively restored sperm count, motility, testosterone levels, and the expression of Catsper1, Catsper2, Catsper3, and Catsper4." (PMID 37754226, 2023). "Mutations of CATSPER1 and CATSPER2 genes have been related to male infertility in humans, and genetic deletion of any of the Catsper genes (CATSPER 1-4) resulted in loss of hyperactivated motility during the time of capacitation in mice." (PMID 32155986, 2020). "An increase in calcium channel components CatSper1 and 2 signals the beneficial potential of MMINA to treat reproductive dysfunction and male infertility." (PMID 36290786, 2022). "To date, association of CATSPER1 (rs2845570), SPATA16 (rs1515442), and TEX11 (rs143246552) genes polymorphism and male infertility was not investigated in Iranian Azeri population." (PMID 35248021, 2022).
asthenozoospermia (16 papers, 2017 to 2025). "Specifically, the exonal CATSPER1 rs1893316 SNP, located in the first exon of the CATSPER1 gene, demonstrated a significant correlation with the risk of idiopathic asthenospermia." (PMID 39469589, 2024). "A separate study enrolled 192 patients diagnosed with idiopathic asthenospermia and 288 healthy control subjects to elucidate the correlation between CATSPER1 single nucleotide polymorphisms (SNPs) and idiopathic asthenospermia." (PMID 39469589, 2024). "Importantly, in the mouse, the invalidation of any of the four pore-forming α subunits gene, CatSper1–4, or the auxiliary CatSperδ subunit gene was shown to cause asthenozoospermia by abrogating Ca2+ influxes and hyperactivated motility." (PMID 35409285, 2022). "This study reported a correlation between CatSper1 mutation and idiopathic asthenospermia." (PMID 29492471, 2017). "The downregulation of CATSPER1 channel in epididymal sperm contributes to the pathogenesis of asthenospermia in rats." (PMID 36766254, 2023). "In our study we have reported a decrease in CatSper1 and CatSper2 gene expression by asthenozoospermia and teratozoospermia groups." (PMID 29492471, 2017). "This suggests that the CATSPER1 SNP (rs1893316) may play a role in the development of idiopathic asthenospermia by influencing the transcription of CATSPER1." (PMID 39469589, 2024). "This suggests that, in humans, mutations in CATSPER genes other than those so far identified (i.e., CATSPER1, 2, and ε) could be responsible for asthenozoospermia." (PMID 35409285, 2022). "In the context of differentially expressed (DE)-genes related to asthenozoospermia, special attention has recently been focused on Cysteine-Rich Secretory Protein 2 (CRISP2), Cation Channel Sperm Associated 1 (CATSPER1) and Prostate and Testis Expressed 1 (PATE1)." (PMID 34440724, 2021). "Genetic defects in CatSper1/2 and in the sperm-specific anion exchanger SLC26A8 that associates with the CFTR channel, have been identified in patients affected by distinct types of asthenozoospermia." (PMID 34205849, 2021). "Not surprisingly, WES has identified a large number of genetic variants relevant to asthenozoospermia, while each variant is likely responsible for just a small fraction of patients, particularly including ADCY1053, CATSPER1-454, EIF4G155, GALNTL556, NSUN757, PLA2G654, SPAG1758, and TRPC559." (PMID 34326689, 2021). "The purpose of this study was to analyze the expression level of CRISP2, CATSPER1, PATE1 and SEMG1 genes in the sperm of men with asthenozoospermia (AZS)." (PMID 31058050, 2019). "In this study CatSper1, 2, 3, 4, KCNU1, Hv1, and TMEM16 ion channel expressions were studied in infertile men with oligoasthenospermia, isolated asthenozoospermia, teratozoospermia, and oligozoospermia in comparison with fertile individuals with normal sperm parameters." (PMID 29492471, 2017).
Obesity (2 papers, 2018 to 2021). Accumulation of substantial excess body fat. "As we found in the survival analyses, 5 DE mRNAs (SORCS1, FLRT3, HIBADH, CATSPER1, and MAP3K8) and 5 DE miRNAs (hsa-miR-3130-2, hsa-miR-148b, hsa-miR-2681, hsa-miR-4487, and hsa-miR-3613) of obesity-related ccRCC were found in VAT." (PMID 34621242, 2021).
oligoasthenoteratozoospermia (2 papers, 2017). A form of male infertility that is characterized by a combination of low number or oligozoospermia, poor motility or asthenozoospermia, and abnormal shape or teratozoospermia of sperms. "Further evidence that CatSper is critical to sperm function comes from the identification of natural mutations affecting CatSper gene family members (‘CatSper 1 and 2’) that are associated with oligoasthenoteratozoospermia." (PMID 28333338, 2017). "The gene expression of CatSper1 revealed an increase by oligozoospermia and oligoasthenoteratozoospermia groups where as CatSper2 gene expression revealed no significant change by oligozoospermia and oligoasthenoteratozoospermia groups." (PMID 29492471, 2017).
varicocele (2 papers, 2018 to 2024). A condition characterized by the dilated tortuous veins of the spermatic cord with a marked left-sided predominance. "The level of CatSper1 and 2 genes expression evaluated using real-time polymerase chain reaction was significantly downregulated 2 months after varicocele induction." (PMID 29766149, 2018). "The epididymal sperm parameters, CatSper1 and 2 genes expression, and testes histology were studied two months after varicocele induction." (PMID 29766149, 2018).
Azoospermia (1 paper, 2022). Absence of any measurable level of sperm,whereby spermatozoa cannot be observed even after centrifugation of the semen pellet. "The aim of this study was to investigate association of idiopathic azoospermia and oligospermia with single-nucleotide polymorphisms of CATSPER1, SPATA16 and TEX11 genes in Iranian-Azeri men." (PMID 35248021, 2022). "We demonstrated a correlation between CATSPER1 (rs2845570) and SPATA16 (rs1515442) genes polymorphisms with idiopathic azoospermia and oligospermia." (PMID 35248021, 2022). "Our finding showed that the CATSPER1 (rs2845570) and SPATA16 (rs1515442) genes polymorphism may play an important role in idiopathic azoospermia and oligospermia in Iranian Azeri population." (PMID 35248021, 2022). "Miscellaneous variants in CATSPER1, SPATA16, and TEX11 genes are identified that play important roles in pathogenesis of sperm morphology (teratozoospermia), sperm motility parameters (asthenozoospermia), or sperm number (oligozoospermia or azoospermia) in human." (PMID 35248021, 2022).
colon cancer (1 paper, 2023). "CATSPER1 is closely related to the poor prognosis of colon cancer and is highly expressed in colon cancer." (PMID 37020597, 2023). "This suggests that CATSPER1 can be used as a therapeutic target for colon cancer." (PMID 37020597, 2023). "The mechanism of CATSPER1 may activate the PI3K/Akt signaling pathway and promote the proliferation of colon cancer cells." (PMID 37020597, 2023).
colorectal cancer (1 paper, 2024). A primary or metastatic malignant neoplasm that affects the colon or rectum. "Functionally, CATSPER1 facilitates the progression of colorectal cancer." (PMID 38586328, 2024). "CATSPER1 can activate the PI3K/AKT signaling pathway at the molecular level and promote the further progression of colorectal cancer, which contradicts Jun Han's." (PMID 38586328, 2024).
cryptorchidism (1 paper, 2020). The failure of one or both testes of a male fetus to descend from the abdomen into the scrotum during the late part of pregnancy. "Therefore, cryptorchidism leads to reduced expression levels of the CatSper1–4 genes in UDTs and impaired fertility in horses." (PMID 31936283, 2020).
hyperthyroidism (1 paper, 2020). Overactivity of the thyroid gland resulting in overproduction of thyroid hormone and increased metabolic rate. "In this study, the effects of hyperthyroidism on Catsper1 and 2 genes of seminiferous tubules in mice testes were investigated." (PMID 32923926, 2020). "The present study was conducted to investigate the effect of hyperthyroidism on the expression of CATSPER1 and CATSPER2 genes in the seminiferous tubules of mice." (PMID 32923926, 2020). "As the findings of the present study indicated, hyperthyroidism has no significant changes in the expressions of both CATSPER1 and CATSPER2 genes." (PMID 32923926, 2020). "With regard to CATSPER1, there was no reaction in all the three segments of the spermatozoa in the hyperthyroidism group." (PMID 32923926, 2020). "According to the importance of cation channel (CATSPER1 and CATSPER2) in motility and the function of sperm, the aim of the present study was to investigate the effect of hyperthyroidism on the expressions of CATSPER1 and CATSPER2 genes in the seminiferous tubules of mice." (PMID 32923926, 2020). "In our study, not only the expression rates of both CATSPER1 and CATSPER2 genes were not significantly different between the hyperthyroidism and control groups, but also the immunohistochemically reactions of anti- CATSPER1 and CATSPER2 antibodies between the two groups." (PMID 32923926, 2020).
teratozoospermia (1 paper, 2017). "CatSper1, CatSper3 gene expression by teratozoospermia patients were detected as lower compared to the controls (p<0.001, p<0.001)." (PMID 29492471, 2017).
tumor (2 papers, 2020 to 2022). "Few studies have focused on the roles of CATSPER1 in tumours; in this study, we found that CATSPER1 was related to HNSCC prognosis." (PMID 35610596, 2022). "Thus, further research on the molecular functions of CATSPER1 in tumours is warranted." (PMID 35610596, 2022). "Based on TCGA analysis for the downregulated genes from our RNA-Seq data, high gene signature comprising of TREM2, CATSPER1, NPL, and PRAM1 in tumor-infiltrating PMN-MDSC predicted poor OS rates in COAD patients." (PMID 33312958, 2020). "In tumor-infiltrating I-MDSC, high gene signature comprising of TNNT1, NPL and CATSPER1 predicted poor OS rates in COAD patients." (PMID 33312958, 2020).
CATSPER1 also shares sentences with these, for which no sentence is quoted: cancer (3 papers); deafness (2); deafness-infertility syndrome (1); dementia (1); genetic disorder (1); hypothyroidism (1); infertility disorder (1); leukemia (1); oligospermia (1).